TLR2 (toll like receptor 2)
Diseases named in the same sentence as TLR2 in open-access papers (continued):
Sharing a sentence is not in itself a finding about the gene and the disease.
ischemia (continued). "Among the Toll-like receptors (TLR), TLR2, TLR4, and their adaptor protein, myeloid differentiation primary-response 88 (MyD88), have been reported to be involved in intestinal ischemia/reperfusion injury." (PMID 30087540, 2018). "HO-1 activator CoPP can reduce the expressions of TLR2, TLR4, IRAK-4 and TRAF6, and markedly increases the expressions of TLR negative regulators, such as SOCS-1, IRAK-M and SHIP-1, in ischemia/reperfusion liver injury in rat." (PMID 29057806, 2017). "There was a significant positive correlation between TLR2, TLR4, IRAK3 and IRAK4 expression and the degree of ischemia as assessed by serum lactate levels and the time until return of spontaneous circulation." (PMID 27260481, 2016). "The protective mechanism of ischemic postconditioning was investigated by comparing its effects on apoptosis, production of the neurotoxic cytokine IL-1β and the transcription and expression of TLR2, TLR4 and IRAK4 in the 2 and 4.5 hour ischemia groups." (PMID 24460643, 2014). "Among Toll-like receptors, TLR2 and TLR4 are found to be more important than others in the pathological progression of cerebral injury due to ischemia and reperfusion." (PMID 23864765, 2013). "Our data also demonstrated that microglial cells mainly expressed TLR2 after DAI, in accordance with previous research that TLR2 were activated in glial cells in response to tissue injury, including trauma, hemorrhagic shock, and ischemia." (PMID 28293064, 2017). "Although it is documented that TLR2 participates in cardiac damage following ischemia, our present results show that this receptor is not involved in the prognosis of heart dysfunction in coronary arteries disease patients." (PMID 26030867, 2015). "We have previously reported that hindlimb ischemia is tolerated well in C57B6 mice lacking TLR4 while those lacking TLR2 developed marked muscle necrosis with poor regeneration and impaired angiogenesis." (PMID 24844636, 2014). "TLR2 and TRIF signaling are necessary for muscle regeneration after ischemia while MyD88 may instead mediate muscle injury." (PMID 23209800, 2012). "To understand whether I/R has an impact on myocardial TLR2 levels, we analyzed TLR2 protein levels in non-ischemic left ventricle myocardium collected at day 3 after ischemia and compared them with those in the left ventricle myocardium of sham-treated hearts." (PMID 35493479, 2022). "When ischemic postconditioning was administered, TLR2 or TLR4 positive staining cells reduced markedly in the 2 hour ischemia group, but not in the 4.5 hour ischemia group." (PMID 24460643, 2014).
leptospirosis (31 papers, 2012 to 2025). A contagious bacterial infection caused by spirochetes of the genus Leptospira. "These insights into TLR2 gene behavior offer a foundation for potential advancements in diagnostic and therapeutic strategies for leptospirosis." (PMID 38014008, 2023). "TLR1 Ile602Ser and TLR2 Arg753Gln gene polymorphisms have also been found to substantially influence the development of severe leptospirosis with jaundice and hepatic insufficiency." (PMID 36551258, 2022). "Noticeably, it has been shown that a specific polymorphism in human TLR2 gene was associated with an increased risk of leptospirosis and influencing its severity." (PMID 27802348, 2016). "These preliminary findings prompt a need for further research to explore the mechanisms underlying TLR2’s role in the pathogenesis of leptospirosis, which may differ in clinical settings compared to laboratory models." (PMID 38014008, 2023). "A study on an Argentinian population suggested that polymorphisms on both tlr2 and in tlr1 genes may confer enhanced susceptibility to severe leptospirosis." (PMID 28270811, 2017). "This Jarisch-Herxheimer reaction occurs after antibiotic treatment of spirochetal infections such as syphilis, Lyme disease, leptospirosis, and relapsing fever, and it is also hypothesized to be caused by the release of bacterial lipoproteins that activate TLR2." (PMID 31557154, 2019). "Nevertheless, certain mouse strains, such as C3H/HeJ and TLR4/TLR-2 double knockout mice, have proven to be valuable experimental models for leptospirosis research." (PMID 41251377, 2025). "Co-injection of L. interrogans serovar Autumnalis and the synthetic TLR2 agonist Pam3cysSK4 in golden hamsters alleviated acute leptospirosis, reduced Leptospira load after three weeks, and mitigated pathological changes in organs." (PMID 39845041, 2024). "TLR2 involvement during the pathogenesis response against leptospirosis was observed through the decrease of IL1β, TNFα, IL6, NFκB, and IL10 secretion/expression due to deficient/knocked down of the TLR2 receptors." (PMID 39729468, 2024). "TLR2 expression is inconclusive during human leptospirosis and further studies are needed to examine the immune effector regulation, through TLR2 for mitigating the harmful effects and promoting effective immune responses." (PMID 39729468, 2024). "It is essential to conduct further human studies to address the ambiguous findings of human TLR2 expression during leptospirosis." (PMID 39729468, 2024). "We assessed the direct TLR2 expression and indirect TLR2 involvement via the secretion/mRNA expression of immune effectors during leptospirosis." (PMID 39729468, 2024). "In the context of leptospirosis, considerable attention has been directed toward Toll-like receptors, particularly TLR2 and TLR4, within the TLR family." (PMID 38476949, 2024). "The contribution of both TLR4 and TLR2 in leptospirosis pathogenesis was observed in DKO mice by showing dramatically low mRNA expression of IFNγ and iNOS, compared with WT mice." (PMID 39729468, 2024). "Direct TLR2 expression against human leptospirosis is inconclusive due to ambiguous findings even in existing human studies." (PMID 39729468, 2024). "Original articles published in English up to January 2024, exploring the role of TLR2 during leptospirosis, were selected from databases including PubMed, Web of Science, Scopus, Trip, and Google Scholar." (PMID 39729468, 2024). "Even though TLR4 is the most defensive PRR in mice/hamster models against leptospirosis, TLR2 contributed to triggering the immune response." (PMID 39729468, 2024). "Although, the review yielded valuable data on the role of TLR2 during leptospirosis, there were equivocal findings on TLR2 direct response." (PMID 39729468, 2024). "Our investigation into the acute phase of leptospirosis using human clinical samples has revealed a downregulation of TLR2 gene expression." (PMID 38014008, 2023).
leptospirosis (continued). "Our study’s key finding is the downregulation of the TLR2 gene expression in human leptospirosis, challenging previous assumptions of TLR2 upregulation in in-vivo and in-vitro studies." (PMID 38014008, 2023). "While in-vitro and animal models have provided insights into the role of TLR2 in Leptospira infection, studies examining innate immune responses and the contribution of TLR2 in human leptospirosis are scarce." (PMID 38014008, 2023). "Knowing the accurate response level of TLR2, is worth to regulate the level of immune effectors secrete during leptospirosis using newly invented therapeutics." (PMID 38014008, 2023). "In contrast to findings of mice models and in vitro studies, in our study, we found four samples showed downregulation of the human TLR2 gene during leptospirosis." (PMID 38014008, 2023). "This study’s primary strength lies in using human samples from confirmed cases of leptospirosis instead of in-vitro or animal studies to study the TLR2 response within a real biological system." (PMID 38014008, 2023). "In the initial cohort of 64 confirmed leptospirosis cases, 18 were selected for human TLR2 gene expression analysis based on criteria of leptospiremia and RNA yield." (PMID 38014008, 2023). "Even though in-vivo and in-vitro studies have suggested the increase of TLR2 expression during leptospirosis, only a few human studies performed the TLR2 response against leptospirosis." (PMID 38014008, 2023). "An immunological basis for pathogenesis of leptospirosis including TLR2 activation is described recently." (PMID 36551258, 2022). "Recognition of leptospires by TLR4 and TLR2 was therefore shown to be essential to the resistance of the murine model to acute leptospirosis." (PMID 35899053, 2022). "Here, we used miRNAs that are differentially regulated by the LPS/TLR2 immune axis to devise a miRNA-based diagnosis for leptospirosis." (PMID 32669469, 2020). "IMPORTANCE Here, we used miRNAs that are differentially regulated by the LPS/TLR2 immune axis to devise a miRNA-based diagnosis for leptospirosis." (PMID 32669469, 2020). "A previous study reported that TLR2 activation during early Leptospira infection protected against leptospirosis in hamsters." (PMID 31675378, 2019). "Many studies have shown that TLRs, particularly TLR2, play a crucial role in the development of leptospirosis." (PMID 31675378, 2019). "During early stages of leptospirosis, leptospiral LPS and outer membrane lipoproteins induce inflammation primarily via Toll-like receptor 2 (TLR2) and in some experiments, via TLR4 activation." (PMID 28750011, 2017). "Other than protective responses resulting from the stimulation of both TLR4 and TLR2, it was shown that leptospirosis induced a TLR2- and TLR4-independent inflammation, also independent from other TLRs." (PMID 28270811, 2017). "It has been found that TLR2 is upregulated on endothelial cells in lung samples of fatal leptospirosis." (PMID 27802348, 2016). "In an effort to investigate the effect of TLR variants, especially TLR2 and TLR4, we genotyped the most studied variants in a high risk population exposed to leptospirosis." (PMID 25255143, 2014). "Although the C57BL/6 strain resists infection with pathogenic Leptospira species, mice with TLR2 and TLR4 double knock-out serve as a model of acute lethal leptospirosis." (PMID 22870312, 2012). "Due to the diversity of the studies in deploying different types of populations, Leptospira whole organism/cell components, different analysis methods, and direct/indirect TLR2 response, it is challenging to make sense of the role that TLR2 plays during human leptospirosis." (PMID 39729468, 2024). "Answering the question on the role of TLR2 during leptospirosis makes it challenging to anticipate how accurately these findings reflect in humans due to the utilization of diverse cell lines and experimental animal models that would not show the real synergistic effect of the human body." (PMID 39729468, 2024).
leptospirosis (continued). "Aligned with our findings, narrative reviews discussed the renal dysfunction associated with leptospirosis that resulted in secretion/expression of Fibronectin, iNOS, CCL2/MCP-1, TNFα, NFκB, CCL2/MIP2, CXCL1/KC through TLR2." (PMID 39729468, 2024). "The involvement of Toll-like receptor 2 (TLR2) in leptospirosis is poorly understood." (PMID 39729468, 2024). "However, increased TLR2 expression was observed in the lung tissues of patients who died because of leptospirosis." (PMID 39729468, 2024). "Also, the scarcity of human studies hinders the establishment of a robust evidence base for interpreting the direct response of human TLR2 during leptospirosis." (PMID 39729468, 2024). "Besides the role of TLR2 in response to leptospirosis, the involvement of TLR4 and TLR5 was identified in in-vitro and in-vivo studies." (PMID 39729468, 2024). "Pam3CSK4 was used in an in-vivo leptospirosis study in order to stimulate TLR2." (PMID 38014008, 2023). "Our study evaluated TLR2 activity in patients with confirmed leptospirosis." (PMID 38014008, 2023). "While TLR2’s role is well-documented in mice, its function in the human response to leptospirosis remains unclear." (PMID 38014008, 2023). "The present study aimed to determine the TLR2 response among confirmed cases of leptospirosis." (PMID 38014008, 2023). "Hence, our study aimed to evaluate the messenger RNA (mRNA) level response of the human TLR2 gene among confirmed cases of leptospirosis by employing a novel exon-exon spanning primer pair for a reliable and efficient RT-qPCR assay." (PMID 38014008, 2023). "Indeed, a specific L. interrogans serovar Autumnalis strain, in which LPS is deprived of contaminating TLR2 activity, induces self-resolving leptospirosis in mice." (PMID 35937697, 2022). "Because it is not known how Leptospira activate TLRs in dogs, we investigated whether canine TLR4 and TLR2 are involved in the recognition of four inactivated Leptospira strains, present in vaccines against canine leptospirosis." (PMID 35386703, 2022). "In mice, which are resistant to leptospirosis, the LPS is recognized by both TLR2 and TLR4." (PMID 36551258, 2022). "Indeed, when studying the general course of leptospirosis, TLR2 and TLR4 play a key role in the control of L. interrogans." (PMID 35899053, 2022). "In addition to TLR4, we also explored the involvement of canine TLR2 in the recognition of four Leptospira strains commonly used in vaccines against canine leptospirosis." (PMID 35386703, 2022). "Thus, identification of an miRNA repertoire responsive to TLR2-mediated LPS signaling will be a valid biomarker for the diagnosis of human leptospirosis." (PMID 32669469, 2020). "Our previous research showed the efficacy of TLR2 agonist Pam3CSK4 against leptospirosis." (PMID 31914888, 2020). "The coinjection of hamsters with L. interrogans serovar Autumnalis and Pam3cysSK4, a synthetic agonist of TLR2, alleviated acute leptospirosis and improved the survival of hamsters, which showed reduced leptospiral loads and histopathological lesions in organs 3 weeks pi." (PMID 33123147, 2020). "In consideration of the modest efficacy of TLR2 agonist Pam3CSK4 against leptospirosis, we hypothesized that TLR4 agonist lipopolysaccharide (LPS) could provide better protection." (PMID 31914888, 2020). "By extension, we may infer that the positive effect on acute leptospirosis previously observed with oral treatment with Lactobacillus plantarum, which is agonist of both TLR2 and NOD2, was probably due to a trained immunity effect." (PMID 31107928, 2019). "In conclusion, host-directed treatment using a TLR2/NOD2 agonist could be envisioned as a novel prophylactic strategy against acute leptospirosis." (PMID 31107928, 2019). "Hence, we focused on TLR2 expression and showed that it was significantly up-regulated during leptospirosis." (PMID 27802348, 2016).
leptospirosis (continued). "Interestingly, TLR2 was significantly increased in leptospirosis but identical levels of CD182 and CD11b were detected when compared to controls." (PMID 27802348, 2016). "Notably, we observed the secretion/mRNA expression of several cytokines (IL6, IL8, IL-1β, TNFα, IFNγ, IL10, CCL2/MCP-1, CCL10, COX2, CXCL1/KC, CXCL2/MIP2) and immune effectors (hBD2, iNOS, Fibronectin, Oxygen, and Nitrogen reactive species) as key aspects of host TLR2 responses during leptospirosis." (PMID 39729468, 2024). "Previous studies using flowcytometry showed increased TLR2 expression on human polymorphonuclear cells and human neutrophils, while one study showed no significant TLR2 expression difference on monocytes of confirmed patients for leptospirosis compared to healthy human samples." (PMID 38014008, 2023). "Indeed, both TLR4 and TLR2 stimulation is important in controlling leptospirosis in mice." (PMID 36551258, 2022). "However, the Argentinian cohort of patients was small, and the SNP found in TLR2 has not been associated with increased susceptibility to leptospirosis in a population from the Azores Islands." (PMID 33123147, 2020). "Interestingly, when the hamsters were coinfected with TLR2 agonist Pam3CSK4 and challenge, hamster survival was increased and kidney, liver, and lung lesions were lessened suggesting that TLR2, and the timing of its response, has a role to play in the control of leptospirosis." (PMID 32922382, 2020). "The human immune system employs pattern recognition receptors like toll-like receptor 2 (TLR2) to detect and combat infections such as leptospirosis." (PMID 38014008, 2023). "Since TLR2 and TLR4 play important roles in protection against leptospirosis and this differential recognition was attributed to co-purified lipoprotein, it was of interest to test the innate activity of our highly pure LPS in different host macrophages." (PMID 37935355, 2023). "In this study, we show that treatment with LPS promoted the gene expressions of TLR2, TLR4, NLRP3 and downstream cytokines, all of which would help control leptospirosis." (PMID 31914888, 2020). "It has been demonstrated that leptospiral LPS activates the plasma membrane Toll-like receptor 2 (TLR2) instead of TLR4 for signaling in humans cells, whereas in mice, which are resistant to acute leptospirosis, both TLR2 and TLR4 recognize leptospiral LPS." (PMID 32932775, 2020). "The early induction of TLR2, TLR4 and inflammatory factor is important for controlling leptospirosis." (PMID 31914888, 2020). "Therefore, β-glucan may exert protective effects against leptospirosis by activating TLR2." (PMID 31675378, 2019). "Emerging evidence has proven that TLR2 and TLR4 play a crucial role in the development of leptospirosis." (PMID 31675378, 2019). "Focusing on TLR2 expression levels on PMN, we observed a significant increase in the leptospirosis group (P = 0.001)." (PMID 27802348, 2016). "We recently showed that TLR2, TLR4, and NLRP3 receptors were crucial in the defense against leptospirosis." (PMID 24498450, 2014). "Our MESV against Leptospirosis demonstrated strong antigenicity, conservation, and safety, successfully eliciting robust immune responses, and showed broad population coverage with strong interactions with TLR4 and TLR2." (PMID 39936152, 2024). "Among TLRs, TLR2 and TLR4 are the most studied in leptospirosis now." (PMID 36551258, 2022). "To date, the levels of the cellular molecules (markers) implicated in PMN response to LPS (TLR2) and cell activation (CD11b, CD15 and CD182) to mediate a robust innate immune response have not been studied in the setting of acute leptospirosis in humans." (PMID 27802348, 2016). "The contention, that TLR2 is the predominant PRR for gram-positive and other bacterial products that are distinct from gram-negative LPS may address the controversial TLR2 expression during leptospirosis even among human/human cell line studies." (PMID 39729468, 2024).